TFRC (transferrin receptor)
Diseases named in the same sentence as TFRC in open-access papers (continued):
Sharing a sentence is not in itself a finding about the gene and the disease.
cancer (continued). "For the current common immunotherapy methods, we also demonstrated that TFRC was co-expressed with various immune checkpoints in several cancers, including PAAD." (PMID 35372510, 2022). "The thematic analysis revealed four themes: transferrin/transferrin receptor-mediated drug delivery to the brain, cancer cells, gene therapy, nanoparticles, and liposomes as drug delivery systems." (PMID 36559067, 2022). "Transferrin receptor 1 (TFR1) expressions are abnormally upregulated in various cancers for the satisfaction of iron demand increased." (PMID 36082181, 2022). "As the TFRC is described as a new cancer marker, the expression of the TFRC in human GIST tissues was assessed." (PMID 36291834, 2022). "Overexpression of transferrin receptor 1 (TfR1) has been confirmed in cancer tissues, which is related to the short survival of cancer patients." (PMID 36497050, 2022). "In another system, cyt c was fused to transferrin, for targeting cancer types in which the transferrin receptor is overexpressed, including lung cancer." (PMID 36479932, 2022). "Transferrin receptor-mediated targeted drug delivery is beneficial in cancer, gene therapy, and diseases or disorders related to the brain because transferrin receptors are present in high concentrations in cancer cells and in the blood–brain barrier." (PMID 36559067, 2022). "For instance, since the transferrin receptor (TfR) is overexpressed in numerous types of cancer cells, transferrin (Tf), which can specifically target TfR, is usually used as a targeting agent." (PMID 36394009, 2022). "Subsequently, we used a butterfly heat map to determine the relationship between TFRC and the activities of the cancer immunity cycle, immunotherapy-positive gene signatures, immune cell infiltration, and immune-relevant genes in PAAD." (PMID 35372510, 2022). "As in many carcinomas, 4T1 cells have an increased expression level of a type 1 transferrin receptor (TfR1) gene." (PMID 35630878, 2022). "In terms of ATC cellular markers, both epidermal growth factor (EGF) receptor (EGFR) and type 1 transferrin receptor (TfR1/CD71) are membrane receptors overexpressed in this type of cancer." (PMID 33808984, 2021). "This ligand binds to over-expressed transferrin receptors (TfR) on cancer cells and triggers cellular uptake." (PMID 35582007, 2021). "Transferrin receptors (TfR) are frequently upregulated on cancer cells, indicating a potential for increased Fe flux." (PMID 34573089, 2021). "In active targeting, particular molecular modifications can be applied for targeting specifically the overexpressed surface receptors of cancer cells, such as folate receptor (FR), transferrin receptor (TfR), or Epidermal growth factor receptor (EGFR)." (PMID 34032937, 2021). "TFRC enhances the proliferation and metastasis of cancer, thereby promoting the progress of cancer, showing the potential of TFRC as a new therapeutic target for human cancer." (PMID 34868339, 2021). "CD71, also known as transferrin receptor protein 1 (TfR1), is vital for the intake of transferrin-iron complexes and is widely expressed in normal cells yet highly expressed in cancer cells." (PMID 34203870, 2021). "Targeting TFRC expression to reduce the amount of iron available to tumors is frequently regarded as a therapeutic strategy in various cancer cells." (PMID 33863873, 2021). "Activation of Ras/mitogen-activated protein kinase signaling increases the sensitivity of cancer cells to ferroptosis and thus leads to the maintenance of relative iron abundance in cancer via control of transferrin receptor and ferritin expression." (PMID 35320929, 2021). "For taking advantage of overexpressive transferrin receptor (TfR) on most cancer cells, T7 peptide, a TfR targeting ligand, was selected as a targeting ligand to facilitate nanoparticles (NPs) internalization in cancer cells." (PMID 33803751, 2021).
cancer (continued). "To this end, we analyzed TFRC mRNA expression based on the multi-cancer cohort data obtained from TCGA using the TIMER." (PMID 34389031, 2021). "It has been reported that YAP can facilitate ferroptosis via up-regulation of a ferroptosis regulator TFRC in cancer cells." (PMID 33928101, 2021). "STEAP family members co-localize with the Transferrin Receptor 1 (TfR1), a mediator of Transferrin-mediated iron uptake, which is up-regulated in many cancers." (PMID 34988012, 2021). "For example, transferrin receptor (TfR) and folate receptors (FRs) are physiologically expressed on various normal cells but overexpressed in many cancer types in response to their higher metabolic rate." (PMID 34209111, 2021). "HFt is effectively taken up and rapidly internalized by virtually all types of cancer cells via the transferrin receptor 1 (TfR1, CD71)." (PMID 33568214, 2021). "The authors proposed that TLD1433-based PDT selectivity for cancer cells relies on its higher accumulation in cancer cells due to a higher expression of the transferrin receptor compared to surrounding healthy tissue." (PMID 34834202, 2021). "The expression of a physiological receptor of ferritin, transferrin receptor 1 (TfR1), is elevated in liver and brain tissue under an inflammatory condition as well as in human cancer cells." (PMID 33203916, 2020). "Both plant and bacterial toxins have been chemically conjugated or fused through DNA cloning to transferrin or to anti-transferrin receptor antibodies to deliver toxic payloads to cancer cells." (PMID 32957689, 2020). "Ricin, gelonin and saporin have been conjugated to both transferrin and monoclonal antibodies against the human transferrin receptor and tested in different cancer settings." (PMID 32957689, 2020). "CD71, or transferrin receptor 1, was previously identified as a therapeutic target for antibody-mediated cancer therapy." (PMID 33603751, 2020). "Further, the transferrin receptor is overexpressed in many cancers where increased expression is correlated with a poor prognosis." (PMID 32957689, 2020). "Through bioinformatics analyses, we demonstrated that the expression of iron-related genes, especially FTH1 and TFRC (which regulate ferritin and the intratumoral iron levels, respectively), were elevated in cancer tissues." (PMID 33204330, 2020). "AFt is recognized by transferrin receptor-1 (TfR-1; upregulated in cancer cells that exhibit high iron demand) and internalized into cells via clathrin-coated pit-mediated endocytosis." (PMID 32443455, 2020). "Due to transferrin receptor overexpression in cancer tissue, a high number of cytoplasmic iron ions from ferritin, which become available for dehydroascorbate, result in production of a significant amount of H2O2 that preferentially targets cancer cells." (PMID 32344912, 2020). "The expression of TFRC in cancer cells is positively correlated with the ferroptotic response induced by artemisinin derivatives or erastin." (PMID 33117818, 2020). "The NDA135b was designed to carry transferrin as a targeting structure to facilitate the uptake of the particle by cancer cells expressing transferrin receptor and decrease the uptake by normal cells including phagocytes." (PMID 31181619, 2019). "High efficacy allows the potential use of this formulation in the therapy of other cancers, since transferrin receptor is overproduced in many types of cancer, especially those that show high growth rates." (PMID 31835393, 2019). "In malignant tissues, TFRC expression is more than in their normal tissues, as cancer cells require large amounts of iron to maintain their high rate of cell proliferation." (PMID 30782157, 2019). "We confirmed that in our system, most (98% ± 1.2) 4T1 cancer cells express transferrin receptor in contrast to 7% (6.6% ± 1.5) of cells present in peritoneal lavage." (PMID 31181619, 2019).
cancer (continued). "The same research team further designed peptides with increased specificity, including the R-Tf-D-LP4 peptide, which contain a transferrin receptor internalization sequence (Tf) to promote the targeting of overexpressed transferrin receptor in cancer cells." (PMID 31261935, 2019). "For targeted delivery, we conjugated RNV541 with a transferrin receptor (TfR) targeting aptamer for TfR-mediated cancer cell delivery." (PMID 31284665, 2019). "The heavy chain (H) subunits of AFt bind to transferrin receptor 1 (TfR1) allowing H-Ft-mediated delivery of iron in times of high iron demand, such as neural development, rapid growth and cancer." (PMID 35582280, 2019). "Transferrin receptor 1 (TFR1) is a broadly expressed transmembrane protein best known for its function in transferrin-bound iron (Tf-Fe) uptake in most cell types, including cancer cells." (PMID 30728365, 2019). "In this work, we aimed at delivering miR-21 into cancer cells by employing a previously developed transferrin receptor (TfR) aptamer." (PMID 31284665, 2019). "Examples of successful active targeting have been demonstrated with nanocarriers conjugated with an anti-transferrin receptor single-chain antibody fragment designed to target cancer cells by binding to the transferrin receptor (TfR)." (PMID 31097014, 2019). "The selectivity of these peptides for cancer cells was addressed by employing the transferrin receptor (hTfR)‐targeting peptide HAIYPRH (Tf) as a cell‐penetrating sequence." (PMID 29698587, 2018). "Our neo-conjugate holds promise for future development to target cancers with enhanced transferrin receptor expression." (PMID 29649293, 2018). "HFn is specifically recognized by the transferrin receptor-1 (TfR1), which is over-expressed in several human cancer subtypes, including TNBC20, and promotes the cellular internalization of these nanoparticles." (PMID 28790402, 2017). "This tranferrin–PEI takes the advantage of highly expressed transferrin receptors (TfR) on many cancer cells." (PMID 28562667, 2017). "Metabolically active cancer cells are known to have elevated bombesin and transferrin receptor levels on the surface." (PMID 28792505, 2017). "Transferrin receptor 1 (a), a cell surface receptor that is responsible for transferrin-mediated iron uptake, is highly expressed in many cancers, including breast cancer." (PMID 28819251, 2017). "Cancer cells show an increase in transferrin receptor (TFR), which is responsible for uptake and regulation of higher levels of intracellular iron levels." (PMID 28216608, 2017). "The transferrin receptor is responsible for major iron homeostasis and supports growth of cancer cells." (PMID 27384479, 2016). "Because malignant cells have increased transferrin receptor expression, this receptor is widely considered as an accessible portal for drug delivery into cancer cells and is becoming a potential target for cancer therapy." (PMID 27384479, 2016). "Since transferrin receptor is overexpressed in cancer cells, these particles can be targeted to cancer cells by using this active targeting in addition to the passive EPR-mediated targeting." (PMID 26352258, 2015). "The endocytosis of transferrin receptor (TfR) has served as a model to study the receptor-targeted cargo delivery system for cancer therapy for many years." (PMID 25803700, 2015). "Transferrin receptor (TfR) is a well-known transmembrane glycoprotein that is overexpressed on the membrane of many cancer cells." (PMID 25778692, 2015). "Transferrin receptor 1 (TfR1) has a key role in cellular iron uptake; TfR1 expression is particularly up-regulated in rapidly growing cancer cells, which need excess iron for their rapid proliferation." (PMID 26426994, 2015). "Cancer cells demonstrate a higher requirement for iron than normal cells and this is emphasized by the increased expression of the transferrin receptor 1 (TfR1), that takes up iron from the iron transport protein, transferrin (Tf), on the cell surface." (PMID 25329549, 2014).
cancer (continued). "In OSCC, the anti-TFRC antibody is suspected to block the internalization of transferrin into cancer cells, and the resulting transferrin deficiency might block the cell cycle and/or induce apoptotic cell death due to the potentially abnormal transferrin requirements of cancer cells." (PMID 24890018, 2014). "A previous study had reported increased expression of transferrin receptor in cancer cells than in normal cells." (PMID 25419056, 2014). "This would be expected to have a somewhat selective impact on the LIP of the many cancers in which the transferrin receptor is highly expressed." (PMID 25279352, 2014). "In malignant tissues, TFRC is expressed more abundantly than in their normal tissue counterparts 10 because cancer cells require large amounts of iron to maintain their high cell proliferation rates." (PMID 24890018, 2014). "The transferrin receptor (TfR) is over-expressed in many cancers and offers an attractive option for the development of transferrin-targeted nanocarriers." (PMID 24795633, 2014). "We found three positive identifiers; TFRC, CEA and CA242 with known biological roles and previous associations to cancer." (PMID 24107468, 2013). "The overexpression of transferrin receptor in cancer cells increased intracellular level of ferrous ions and, presumably, increased the rate of the Fenton reaction." (PMID 24454991, 2013). "Cancer cells overexpress transferrin receptors making the glycoprotein, transferrin or antibodies to transferrin receptor, suitable ligands for tumor targeting." (PMID 23533772, 2013). "The enhanced metabolic need for iron in cancer cells is well-established, and the up-regulated transferrin receptor is being investigated as a means to specifically target cancer cells." (PMID 24391728, 2013). "Among these cancer biomarker candidates, TFRC, MET and VEGFA are commonly amplified genes in tumors and their encoded proteins stained positive in more than 80% of malignancies from public databases." (PMID 22761861, 2012). "The targeted toxins bind to a surface antigen or receptor overexpressed in cancer, such as the epidermal growth factor receptor, transferrin receptor, interleukin-13 or interleukin-4 receptor." (PMID 22069569, 2010). "Conversely, a number of studies have reported a distinct correlation between higher levels of TFRC expression and increased cellular proliferation in cancer cells." (PMID 19259415, 2008). "The iron-binding protein, transferrin, is internalized into cancer cells after binding to the transferrin receptor (TfR, CD71)." (PMID 17726528, 2007). "At present, the transferrin receptor is commonly used for cancer-targeted drug delivery systems including cationic liposomes." (PMID 16792817, 2006). "Additionally, the transferrin receptor TfR, which is upregulated in certain cancer cells, has emerged as a potential therapeutic target." (PMID 39968416, 2025). "The high affinity and specificity of these aptamers for TFRC make them ideal candidates for the development of novel cancer therapeutics that could improve patient outcomes." (PMID 40303995, 2025). "Moreover, ligands such as transferrin (Tf), which are abundantly expressed on cancer cells, can bind to transferrin receptors (TfR) inherently present on EV surfaces, so enabling targeted delivery." (PMID 40530018, 2025). "This study supports the use of ferroptosis to enhance the efficacy of HGSC treatment and suggests that modulating TFRC levels may be an effective strategy against drug resistance in various cancers." (PMID 40697100, 2025). "Moreover, the discussion on the role of Fe should include the function of the transferrin receptor and its overexpression in cancer cells, which meets the heightened Fe demand in these cells." (PMID 38999951, 2024). "Targeting IGF2BP2 and TFRC may represent innovative approaches for the diagnosis and treatment of cancer." (PMID 38602575, 2024).
cancer (continued). "modified the transferrin receptor of blood-derived exosomes with magnetic nanoparticles and subsequently utilized external magnets to direct the exosomes to mouse tumors, thereby creating targeted drug delivery vehicles for cancer therapy." (PMID 39684778, 2024). "Here, we determined that LASS2 interacts with TFRC in these specific cancer cell types." (PMID 38419028, 2024). "Several genes, including the transferrin receptor, ferritin heavy chain, ferritin light chain, iron exporter ferroportin, iron regulatory protein 2, and LCN2, have been implicated in the regulation of iron in cancer cells." (PMID 39850877, 2024). "In SIRT3-deficient cells, the heightened production of ROS enhances IRP1’s binding affinity to IREs, leading to the aberrant upregulation of iron-related genes such as the transferrin receptor (TfR1), which governs iron uptake and promotes cancer cell proliferation." (PMID 39682281, 2024). "Even ex vivo lymphocytes and monocytes vary in the expression of HC-10-reactive forms when healthy controls and patients with malignancies are studied, with possible physiological implications, from the modulation of intracellular signals to the regulation of transferrin receptor endocytosis." (PMID 39273322, 2024). "The protein levels of TFRC in various cancer tissues were examined via IHC." (PMID 38419028, 2024). "The expression of TFRC in cancer cells is correlated with heightened iron requirements for cell proliferation, positioning it as a potential target for inducing ferroptosis in cancer treatment." (PMID 38562143, 2024). "Moreover, our study has revealed the previously unreported direct interaction between LASS2 and TFRC in various cancers." (PMID 38419028, 2024). "Meanwhile, TFRC has been verified to be abnormally expressed in various cancers." (PMID 37675227, 2023). "We found that TFRC knockdown inhibited cancer progression via the PI3K/Akt/mTOR signaling pathway." (PMID 37644594, 2023). "The results indicate that T7‐CMNVs may transfer AMO21c into transferrin receptor‐expressing cells, such as cancer cells and endothelial cells." (PMID 36925699, 2023). "The expression of TFRC is enhanced in ccRCC tumors and correlates with cancer progression." (PMID 36604669, 2023). "It is notable that oncogenic RAS-harboring cancer cells (such as HT1080) display increased iron content relative to their normal cell counterparts due to an upregulation of transferrin receptor 1 and downregulation of ferritin heavy chain 1 and ferritin light chain." (PMID 37299622, 2023). "Many receptors are known to be overexpressed in cancer cells, like folic acid receptor (FR), transferrin receptor (TfR), or epidermal growth factor receptor (EGFR), which have been explored as docking sites for selective targeting of anticancer chemotherapeutics." (PMID 36678830, 2023). "Previous research has proposed that ruthenium complexes, including KP1019, preferentially accumulate in cancer cells compared to non-cancer cells through transferrin receptor-mediated endocytosis, attributed to the heightened expression of these receptors on the surface of cancer cells." (PMID 38256884, 2023). "In most cases, especially in cancerous diseases, it was reported that elevation of TFRC could sensitize cancer cells to ferroptosis, as well as other cell types." (PMID 36950524, 2023). "Furthermore, more frequently upregulated TFRC expressions occur in some drug-resistant human cancer cells, therefore requiring more in-depth studies to clarify the role of TFRC in the sensitivity and resistance of cancer cells to imatinib in GIST therapy." (PMID 37675227, 2023). "However, the mechanism whereby TFRC expression is maintained at high levels in iron‐enriched cancer cells and the contribution of TFRC to cancer development are enigmatic." (PMID 36703617, 2023).